CTLA4 (cytotoxic T-lymphocyte associated protein 4)
Diseases named in the same sentence as CTLA4 in open-access papers (continued):
Sharing a sentence is not in itself a finding about the gene and the disease.
cancer (continued). "Indeed, similar to the negative feedback mechanisms regulating T cells, activated NK cells express PD-1, CTLA4, TIM3, LAG3, and other immune checkpoint receptors, explaining why NK cells become increasingly dysfunctional with cancer progression." (PMID 36175961, 2022). "As previously reported, in the cancer-immunity cycle, CD28: (CD80, CD86), CD40, CD27, HVEM, GITR: GITRL, ICOS, and TLR-2 are stimulatory factors, while TIM-3, PD-L1: PD-1, PD-L1: (CD80, CD86), CTLA-4: (CD80, CD86), BTLA, and LAG-3 are inhibitory factors." (PMID 35419462, 2022). "There was, however, a significant association between a high CTLA-4/CD3-ratio and absence of nodal metastases in 1756 cancer samples (p = 0.0354)." (PMID 35091676, 2022). "PD-1, PD-L1, CTLA-4, and LAG-3 are currently approved therapeutical targets in cancer therapy." (PMID 36263134, 2022). "The IPRP score and CTLA4 expression were significantly correlated in 9 cancers, among which there were negative correlations in BRCA and KIRC, and the others were all positively correlated." (PMID 35945345, 2022). "In other cancers, immunotherapy, which harnesses the body’s immune system, has recently made historic breakthroughs through clinical successes via the use of immune checkpoint blockade (ICB) against both the CTLA-4 and PD-1 systems." (PMID 35920986, 2022). "Interestingly, our research also found that LINC00857 expression was negatively related to the expression of immune checkpoint genes including PD1, CTLA4 and PD-L1 in LINC00857 high-expressing cancers." (PMID 36160408, 2022). "In addition to PD-1 and CTLA-4, BTLA is also an immune checkpoint, and is ligated by HVEM to inhibit T cell activation and survival, hence BTLA blockade can enhance cancer immunotherapy." (PMID 36552785, 2022). "Besides, our research manifested the correlation of SLC7A11 with 8 IC genes, namely CD274 (also known as PD-L1), HAVCR2, LAG3, SIGLEC15, PDCD1LG2, CTLA4, PDCD1, and TIGIT in 33 cancer types." (PMID 36267158, 2022). "Further, the combined application of HDACi and antibodies against CTLA-4 could facilitate CD4+T cell infiltration and exert a synergistic effect on cancer treatment by intensifying anticancer immune responses." (PMID 35585975, 2022). "A canine CTLA-4 monoclonal antibody has recently been developed for comparative oncology research; however, it has not been evaluated yet in canine cancer patients." (PMID 36698398, 2022). "Thus, in line with several classical immune checkpoints (PD-1/PD-L1 and CTLA-4), the blockage of the CD73-adenosine axis has been considered a grand promise for further improving clinical outcomes in cancer patients." (PMID 36428755, 2022). "In addition, recent studies showed that anti-CTLA-4 and anti-PD1/PD-L1 combination therapy activates T cells during cancer treatment." (PMID 35528238, 2022). "Since HER-2 is not expressed in TNBC diagnosis, the production of nanobodies for the diagnosis and treatment of cancer cells should be performed against other antigens expressed in TNBC such as TNF-α, EGFR, CD3, CTLA-4, STAT3, AKT2, GTP-binding protein Rho, CapG, fibronectin, and CA-IX." (PMID 35933373, 2022). "Since CTLA-4 is expressed on DCs and has a significant effect on diminishing their function, we aimed to inhibit the expression of CTLA-4 in CRC cell lysate-pulsed-DCs via transfection of siRNA to enhance the efficacy of DC-based cancer immunotherapy." (PMID 35979362, 2022). "Immune checkpoint inhibitors (ICI) based on anti-CTLA-4 (αCTLA-4) and anti-PD1 (αPD1) are being tested in combination with different therapeutic approaches including other immunotherapies such as neoantigen cancer vaccines (NCV)." (PMID 35110563, 2022). "Moreover, correlation analysis hinted at a negative correlation of TMEM59L expression with CD8 T cells, activated CD4 T cells, and several immunomodulators, including IDO1, TIGIT, PD-L1, CTLA-4, and BTLA in various cancers." (PMID 36618425, 2022).
cancer (continued). "In addition, five PRIs (HHLA2, IL2RA, TNFRSF18, TNFSF14, and CTLA4) included in the signature were regarded as potential PLAUR-related biomarkers in KIRC, which were studied in other cancers including KIRC based on the current literature." (PMID 36052236, 2022). "When the FDA approved the CTLA-4 monoclonal antibody Ipilimumab as an immunotherapy for metastatic melanoma in 2011, it was the first time an ICI had been approved for clinical use as a cancer immunotherapy medicine." (PMID 36248998, 2022). "Anti-CTLA-4 and anti-PD-1/PD-L1 immune checkpoint inhibitors are therapeutic monoclonal antibodies that do not target cancer cells but are designed to reactivate or promote antitumor immunity." (PMID 35033167, 2022). "Since CTLA-4 has a significant regulatory impact on immune responses, antibodies against either mouse or human CTLA-4 have been established to support immune responses against cancer." (PMID 35999569, 2022). "CTLA-4 blockades can enhance the metabolic fitness of CD8+T cells and destabilize Tregs in glycolysis-defective tumors, indicating that the combination of CTLA-4 blockers and glycolysis inhibitors is a promising strategy in cancer." (PMID 36200045, 2022). "Moreover, the link between CTLA4, PDCD1, CD86, CD274, and ISCA1 in various cancer types was measured." (PMID 36072584, 2022). "PDCD1, CTLA4, TIM3, TIGIT, and LAG3 play key roles in the immune evasion of cancer cells." (PMID 34844217, 2021). "More important, LAG3 may synergize with CTLA4, PD1/PDL1, and other immune checkpoints, thereby contributing more evidence to improve combination cancer immunotherapy by simultaneously targeting LAG3, PD1/PDL1, and CTLA4." (PMID 34267742, 2021). "Whereas ligand engagement of CD28 activates T cells, interaction between CTLA-4 and these ligands inhibits T-cell stimulation, thereby promoting a negative feedback loop that prevents T cells from killing cancer cells." (PMID 33946818, 2021). "Combining anti-CTLA4 agents, such as ipilimumab, and PFKFB3 might simultaneously reinforce the immune reaction to cancer and attenuate cancer cell metabolism." (PMID 33671514, 2021). "Ipilimumab, anti-CTLA-4 antibody, was the first ICI to be approved for clinical use in cancer." (PMID 34578321, 2021). "The importance of the discovery of inhibiting negative T lymphocyte regulators to treat cancer was recognized in 2018 by the award of the Nobel Prize in Physiology or Medicine to James P. Allison (CTLA-4) and Tasuku Honjo (PD-1)." (PMID 34073258, 2021). "Tumor cells may escape immune recognition through the downregulation of MHC class I expression, production of immunosuppressive cytokines such as TGF beta, IL10, and immune checkpoint proteins expressed on the cancer cell such as PDL1, CTLA-4, and TIGIT." (PMID 34769455, 2021). "In cancer, suppression of immune responses can be carried out not only by MDSCs or Tregs, but also by both CTLA-4 and PD-1 pathways." (PMID 34572849, 2021). "We further explored the correlation between YTHDC2 and eight immune checkpoint‐related genes and found that YTHDC2 was significantly associated with the expression of SIGLEC15, IDO1, CD274, HAVCR2, PDCD1, CTLA4, LAG3 or PDCD1LG2 in almost all types of cancers except for CESC and TGCT." (PMID 34312987, 2021). "The breakthrough discovery of immune checkpoints such as cytotoxic T-lymphocyte antigen 4 (CTLA-4) and programmed cell death 1 (PD-1) had led to the development of immune checkpoint inhibitors (ICI) resulting in substantial changes in cancer treatment paradigms." (PMID 33890870, 2021). "Further, combined anti-CTLA-4/B7 and anti-PD1/PD-L1 therapy has been applied to cancer treatment." (PMID 34088360, 2021). "A study had shown that the recurrence rate of the same irAEs resulting in discontinuation of ICI treatment in cancer patients who rechallenged the same ICI was 28.6% (anti-PD-1 or anti-PD-L1 monotherapy), 47.4% (anti-CTLA-4 monotherapy), and 43.5% (combination therapy), respectively." (PMID 34458371, 2021).
cancer (continued). "The anti-CTLA4 mAb, ipilimumab, the first immune checkpoint inhibitor for immunotherapy of cancer patients, blocks negative signals on effector T cells, but can also deplete Treg cells or block Treg suppression." (PMID 34882757, 2021). "No trial using PD-1/PD-L1 or CTLA-4 monoclonal antibodies as an intervention in patients with early malignant tumors reported the HRs for mortality outcomes by sex." (PMID 34086601, 2021). "But well-established ICIs, including blockades targeting CTLA-4 and PD-1/PDL-1, only apply to a subset of cancer patients due to heterogeneous gene expressions and microenvironment across various cancer types, and as such novel therapeutic targets need to be considered." (PMID 33954112, 2021). "An influential clinical trial whereby improved survival rates were seen when patients with unresectable melanomas (stage III/IV) were treated with an anti-CTLA-4 monoclonal antibody ultimately led to the FDA approval of the first immune checkpoint inhibitor, ipilimumab, for cancer therapy." (PMID 34268109, 2021). "Furthermore, the administrations of immune checkpoint modulators (such as anti-CTLA4 and anti-PD antibodies) and adoptive immune cells (such as CAR-T) have exhibited unexpected antitumor effect in various cancers." (PMID 34746236, 2021). "Furthermore, some studies reported that, in various cancers, EMT showed a strong correlation with immune activation, and had high expression of programmed cell death-1 (PD-1), PD-L1, CTLA4, OX40L and PD-L2." (PMID 33435173, 2021). "Anti‐TGF‐β antibodies rendered TGF‐β‐responsive cancer stem cells sensitive to adoptive T‐cell transfer treatment, of which the efficacy could be hindered by CD80/CTLA4‐mediated immunosuppression." (PMID 33932112, 2021). "Most of the studies on CTLA-4 have been committed to CTLA-4 membrane protein, especially in the field of cancer research, however, the gradual unraveling of the significant role of soluble form in immunosuppressive function is now attracting attention toward soluble form as well." (PMID 34006227, 2021). "Despite the obvious efficacy of PD‐L1, PD‐1, and CTLA‐4 suppression in cancer therapy, not all patients responded to these treatments." (PMID 33369247, 2021). "Unlike the CD28, CTLA-4 increases T cell activation and reduces the immune response against cancer cells." (PMID 34193050, 2021). "Discovery of the B7 family immune checkpoints such as CTLA-4 (CD152), PD-1 (CD279), as well as their ligands B7-1 (CD80), B7-2 (CD86), B7-H1 (PD-L1, CD274), and B7-DC (PD-L2, CD273), has opened new possibilities for cancer immunotherapy using monoclonal antibodies (mAb)." (PMID 33419027, 2021). "Blockage of the PD-1/PD-L1 or CTLA4 signal with antibodies prevents binding of immunosuppressive molecules to cytotoxic CD8+ T cells, which maintains cytotoxic CD8+ T cell activity against cancer cells." (PMID 33406733, 2021). "The emergence of cancer immunotherapeutics that target cancer-related T cell dysregulation such as the currently approved immune checkpoint inhibitors based on PD1, PD-L1, and CTLA-4 have encouraged the investigation of additional checkpoint pathways as immunotherapeutic targets." (PMID 34926643, 2021). "MMR-deficient cancers are now acknowledged to be sensitive to anti-PD1 (nivolumab, pembrolizumab) with or without anti-cytotoxic T-lymphocyte-associated protein 4 (CTLA-4) antibodies." (PMID 34945805, 2021). "Furthermore, we found that LCK was significantly correlated with TIGIT (total rho=0.82), CTLA4 (total rho=0.77), and PD-1 (total rho=0.81) in most cancer types, indicating the important role of TIGIT, CTLA4, and PD-1 in the TIL-T cells across cancer types." (PMID 35069521, 2021). "This, in keeping with the concept of immune checkpoint blockade, where host immune regulators (such as CTLA4 and PDL1) show a dramatic effect on cancer progression (regardless of cancer genetic mutations or subtypes)." (PMID 35201443, 2021).
cancer (continued). "In conclusion, in this up-to-date meta-analysis of all the available studies on immunotherapy in advanced or metastasized cancer, there were no sex differences in the efficacy of PD-1/PD-L1 or CTLA-4 inhibitors." (PMID 34086601, 2021). "Meanwhile, Siglec15 was positively related to PD-L1, PD-1, CTLA-4, and LAG-3 in most cancers." (PMID 33537076, 2021). "Although the CTLA-4 expression profile does not stay steady along with cancer progression, the over-expression of CTLA-4 seems to be a noticeable cancer-biomarker." (PMID 35083014, 2021). "Moreover, CTLA4, PDCD1 (PD-1), and CD274 (PD-L1), as the primary immune checkpoints in cancers, had the highest expression level in IS2 and the lowest level in IS1 (p < 0.05)." (PMID 34404444, 2021). "The CTLA4, TOB1, MYC, Notch, Hedgehog, and EMT pathways play a critical role in cancer progression." (PMID 34095215, 2021). "Although the immune-related adverse events of anti-CTLA-4 mAb treatment are frequent and sometimes severe, anti-CLTA-4 treatment is the first proof-of-concept therapeutic strategy for checkpoint inhibition in cancer immunotherapy." (PMID 33801815, 2021). "Nonetheless, it should be underscored that the use of anti-CTLA-4 was probably not the most favorable investigational agent for the IO arm in view of its low overall efficacy as monotherapy in the treatment of cancer in general." (PMID 34926989, 2021). "Not unexpectedly, a significant positive correlation was found between the reporting odds ratio (ROR) of reporting an irAE during anti-CTLA-4, anti-PD-1, and anti-CTLA-4/anti-PD-1 immune combination therapies and the corresponding TMB in 7677 patients across 19 cancer types." (PMID 33151369, 2021). "Immune exhaustion marker genes (such as PD-L1, CTLA-4, LAG-3 and HAVCR2) have been demonstrated to play significant role in immune suppression in multiple tumors and several target inhibitors have also been widely applied to immunotherapy for cancers." (PMID 34844602, 2021). "Therefore, in cancer patients receiving anti-PD1, anti-PDL1, or anti-CTLA4 drugs, regular endocrine assessment is recommended to make early diagnosis and appropriate treatment." (PMID 34539667, 2021). "However, T cell activation is often blocked by immune checkpoint molecules (including PD-1/PDL1, CTLA-4, and TIM-3) in individuals with cancer." (PMID 35047022, 2021). "CTLA4 and PDCD1 are immune checkpoint inhibitors that can be targeted for cancer immunotherapy." (PMID 34252931, 2021). "Cancer cells evade the host’s immunity by inhibiting immune effector cells, particularly cytotoxic (CD8+) T cells, by employing immune checkpoint pathways, such as programmed cell death-1 (PD-1) and cytotoxic T-lymphocyte antigen-4 (CTLA-4)." (PMID 33931473, 2021). "The role of the Fc-FcƳR interaction for the therapeutic efficacy of anti-CTLA4 therapy in human cancer patients is still not clear." (PMID 34675296, 2021). "These ICIs restore anti-cancer immune responses through neutralization of negative regulation mediated by PD-1 or CTLA-4-mediated signaling pathways." (PMID 33665689, 2021). "Cytotoxic T-lymphocyte protein 4 (CTLA-4) and programmed death receptor-1 (PD-1) signals play vital roles in the immune escape, and they are increasingly being recognized as immunotherapy targets in several advanced cancers." (PMID 34795662, 2021). "In addition, the 5mC score was negatively correlated with the expression of four critical immune checkpoints, PD-L1, PD-1, CTLA-4, and LAG-3, in most cancers." (PMID 34836536, 2021). "PD-1 is more extensively expressed on activated cells than CTLA-4 and predominantly modulates effector CTL responses upon interaction with its ligand, programmed death-ligand 1 (PD-L1; B7-H1; CD274) and/or PD-L2 (B7-DC; CD273) on cancer cells." (PMID 33808294, 2021). "Increased expression of CTLA-4 and PD-1/PD-L1 and their negative correlations with overall survival (OS) in various cancer cases have been well-established." (PMID 32760400, 2020).
cancer (continued). "Therapeutically, inhibiting the negative T cell regulators CTLA4 and PD-1 has resulted in dramatic responses in patients with cancer who previously had grave prognosis." (PMID 32814710, 2020). "Particularly because there is a significant correlation of lymphatic PD-1 or CTLA-4 with lymphatic NR2F6 expression in human NSCLC patients, we wanted to determine whether acute Nr2f6 inactivation enables anti-cancer activity in vivo." (PMID 31937317, 2020). "In some cancers including colorectal cancer, the blockade of CTLA-4 or PD-1 does not achieve an ideal therapeutic effect and incentivizes the efforts to locate other immune checkpoint inhibitors, such as TIM3." (PMID 33084973, 2020). "CTLA-4 and PD-1/PD-L1 are the two best-studied co-inhibitory pathways; the use of antibodies as immune checkpoint inhibitors, anti-CTLA4 antibodies, and anti-PD-1/PD-L1 antibodies has been approved for the treatment of several cancers." (PMID 33251233, 2020). "Based on our comprehensive review of the current literature, we conclude that anti-PD-1/PD-L1- and/or anti-CTLA-4-based cancer treatment does not appear to increase vulnerability for SARS-CoV-2 infection per se." (PMID 33207589, 2020). "Our investigation, therefore, studied the relationship between serum CTLA-4 and standard inflammatory markers, namely the pro-inflammatory cytokines, TNF-α and IL-6, which have emerged as central players linking inflammation and cancer." (PMID 32123292, 2020). "Inhibition of the immune checkpoints with anti-CTLA4, anti-PD-1, or anti-PD-L1 antibodies represents the most notable approach in the current cancer immunotherapy." (PMID 32824578, 2020). "In addition to PD1/PDL1 and CTLA4, other “metabolic checkpoints” (e.g., mTOR, PGC-1α, IDO1, LDH) have been identified as affecting the competition between cancer and infiltrating immune cells for nutrients and metabolites." (PMID 33178201, 2020). "Furthermore, in terms of cancer types, relatively higher expressions of PD-1 and CTLA4 in SARC and SKCM compared to the others, elevated expressions of PD-L2 in GBM, SARC and SKCM, and similar levels of PD-L1 expressions across cancer types were observed." (PMID 32533054, 2020). "Importantly, therapeutics aimed at alleviating immune suppression, such as anti‐CTLA‐4 and anti‐PD1 antibodies, have shown persistent clinical responses in a number of cancer types." (PMID 32923989, 2020). "The results of their experiments in the mouse melanoma model demonstrated that intratumoral injection of cGAMP enforced anti-cancer CD8+ T cell responses, and this ability could be further enhanced when both PD-1 and CTLA-4 were blocked." (PMID 32571374, 2020). "Immunotherapy using immune checkpoint blockade (ICB), such as anti-CTLA4 and anti-PD1 antibodies, has revolutionized cancer treatment and has generated durable therapeutic responses in a significant subset of patients across a variety of cancer types." (PMID 32358507, 2020). "The research implies that triple therapy (RT + anti-CTLA-4 + anti-PD-1/PD-L1) in various cancer types is not redundant for cancer treatment." (PMID 32992835, 2020). "Immune-checkpoint inhibitors, targeting programmed cell death-1 (PD-1), programmed cell death ligand-1 (PD-L1), or cytotoxic T-lymphocyte protein 4 (CTLA-4), can specifically block the corresponding immunosuppressive signals and exhibit potential efficacy on malignant tumor including advanced HCC." (PMID 33330071, 2020). "Both CTLA4 and LAG3 have been considered as the immune checkpoint targets in cancer immunotherapy." (PMID 33457419, 2020). "Targeting IC molecules including CTLA-4, TIGIT, PD-1, GITR, etc. on Tregs may be effective for cancer treatment." (PMID 32680511, 2020). "PD-1 and CTLA4 were significantly correlated with CD8+ T cell but not CD4+ naïve T cell counts in most cancers." (PMID 33072070, 2020).